CD44 (CD44 molecule (IN blood group))
Diseases named in the same sentence as CD44 in open-access papers (continued):
Sharing a sentence is not in itself a finding about the gene and the disease.
tumor (continued). "Compared to single circulating tumor cells (CTCs), our recent studies have demonstrated that CD44-mediatd cell aggregation enhances the stemness, survival and metastatic ability of aggregated cells." (PMID 37866630, 2023). "Increased sensitivity of HA to CD44 help these active targeting of the NPs to accumulate inside tumor and therefore provide a promising antitumor response." (PMID 37283735, 2023). "The ratio of tumor-infiltrating CD44+/CD8+ T cells was around 90%, indicating tumor antigen experience." (PMID 37208329, 2023). "CD44 is a transmembrane glycoprotein that is a marker of tumor stem cells and is directly involved in tumor development." (PMID 36964570, 2023). "Considering that Merlin inhibits putative tumor-promoting functions of CD44 (as discussed in the introduction), we expected that deletion of Nf2 would lead to more a severe phenotype in Cd44-positive mice when compared to Cd44-negative equivalents." (PMID 37174657, 2023). "Of patients with highly expressed CD44, 57.2% had a grade 3 tumor compared with 19.6% of patients with low CD44 expression (p = 0.0084)." (PMID 36831554, 2023). "Immunohistochemistry (IHC) staining was performed using (i) PD-L1 antibodies to detect PD-L1 expressions; (ii) CD8 and CD4 to detect Tumor Infiltrating Lymphocytes (TILs); and (iii) CD44, LGR5, and ALDH2 to detect stem cell markers." (PMID 36604635, 2023). "Within the postoperative tumor microenvironment, the p-selectin protein present on the surface of platelet membranes interacts positively with CD44, the corresponding surface receptor on 4T1 cells." (PMID 38140108, 2023). "It is assumed that the discoveries are attributed because CD44 is released from malignant cells, which reflect the tumor mass in AL." (PMID 37627214, 2023). "The HA-Lip-HNK exhibited higher tumour accumulation, with a tumour growth inhibition rate of 60% where increased CD44-HA interaction was confirmed by confocal microscopy." (PMID 38112935, 2023). "IHC staining of tumor sections showed a significant decrease in CD44 expression, while HE staining showed a significant decrease in tumor aggressiveness." (PMID 37351164, 2023). "A pan-CD44 mAb, C44Mab-46, recognized not only tumor cells but also stromal tissue and probably immune cells, which are important for antitumor immunity." (PMID 37189717, 2023). "We also observed a statistically significant increase of CD4+ T cells infiltrating the tumor with an effector memory phenotype (CD44+, CD62L-) consistent with the induction of a strong and long-lasting antitumor response." (PMID 38152397, 2023). "CD44 has roles in cell–cell interactions, cell adhesion and migration, lymphocyte activation and homing, hematopoiesis, and tumour metastasis." (PMID 37762403, 2023). "This is an important ligand for CD44-positive macrophage differentiation at the GB site attenuating tumor immunogenicity and, consequently, promoting GB growth." (PMID 38074665, 2023). "As demonstrated in tumor cells during angiogenesis, CD44 mediates cell surface localization of MMP9 and MMP2 and is thereby also implicated in TGF-β1 activation." (PMID 37894778, 2023). "Binding between CD44 and HA mediates tumor cell adhesion to the peritoneum, hence promoting intraperitoneal OC spread." (PMID 37274261, 2023). "Tumor-associated macrophages (TAMs) increased CSC fraction by elevating the level of hyaluronic acid in ECM, and subsequent stimulation of CD44/PI3K pathway." (PMID 37453969, 2023). "The expression of CD44 in tumor cells is closely related to the prolonged PFS and OS, which can be used as an independent evaluation factor to predict the clinical benefits of patients receiving PD-1 inhibitor treatment." (PMID 37671151, 2023). "MSC CM was enriched with Moesin (MSN), which acted as an extracellular tumor-suppressing protein by interacting with CD44." (PMID 37699930, 2023).
tumor (continued). "The proliferation rates of CD133+/CD44+ and total cells were further monitored in tumor-derived sections using immunohistochemical staining for Ki67." (PMID 36831395, 2023). "Adoptive transfer of CD62L+CD44− naïve OT1 CD8+ T cells to Tipe2ΔNK/ΔNK mice or control mice bearing MC38‐OVA tumors showed that donor‐derived tumor‐infiltrating OT1 CD8+ T cells in Tipe2ΔNK/ΔNK mice expressed higher levels of IFN‐γ and TNF‐α." (PMID 36807566, 2023). "Taken together, we suggest that COL1A1 in fibroblasts and CD44 epithelial/malignant cells interact interdependently, facilitating tumor progression." (PMID 36828832, 2023). "ALDH1A1 and CD133 positivity was only identified in tumor cells, while CD44 was present in tumor cells and tumor-surrounding stroma cells." (PMID 36768723, 2023). "CD44 expression has been positively correlated with tumor aggressiveness and the response of bladder cancer to radiation, as well as associated with drug-resistant phenotype and poor prognosis." (PMID 37110670, 2023). "Further immunofluorescence staining of α-SMA or CK18 with CD44 confirmed the increased CD44 expression in CK18 positive tumor cells." (PMID 37507768, 2023). "Here, we report that HABN administered intravenously (IV) accumulates in CD44-expressing tumor cells and TAMCs." (PMID 37553327, 2023). "Targeting the Spp1-Cd44 axis restored T cell function in vitro and significantly reduced tumor burden when treated with either anti-Spp1 or anti-Cd44 antibody alone or in combination with anti-Pd-1 antibody in the mouse model." (PMID 37336873, 2023). "We demonstrate that mCNT surface functionalization using CD44 antibody enhances its tumor tissue enrichment and retention, thereby increasing efficacy in treating GBM in mice." (PMID 36989359, 2023). "Several studies have revealed the central role of high CD44 expression in carcinogenesis, tumor growth, differentiation, and tumor metastasis in CRC." (PMID 36831554, 2023). "After ingesting by tumor cells via CD44 mediated endocytosis, the acidic condition in cell lysosome will further trigger the protonation of TA molecules, leading to the Fe3+ release of nanoprobe." (PMID 36597067, 2023). "Overexpression of CD44 or CD133 is significantly associated with clinical TNM stage, tumor differentiation, lymph node metastasis, and a decreased 5-year overall survival rate." (PMID 37173787, 2023). "Park and group reported PEGylated hyaluronic acid (HA)-coated exosomes to target the CD44-overexpressing cells actively and verified the targetability using the RA and PC3 tumor-bearing mouse models, representative models of CD44-overexpression." (PMID 37635253, 2023). "In particular, in contrast to intracellular moesin, extracellular moesin exerts a tumor-suppressive effect by regulating cell adhesion through inhibition of Src and β-catenin signaling via its interaction with the CD44 extracellular domain and FN1." (PMID 37894408, 2023). "We found that tumor cryosections with a positive potential difference correlated with higher rates of tumor spread in patients and higher expression of CD44—a known CSC marker." (PMID 36925705, 2023). "The status of mesenchymal stem cell markers, CD105 and CD44, were significantly elevated in expression in the metastatic ccRCC compared to primary tumours." (PMID 37174052, 2023). "Since CD44 is a cell surface adhesion receptor, we evaluated the potential role of the MSN-CD44 regulatory axis in the observed tumor-suppressing capabilities and expression of K-Ras in PDAC cells." (PMID 37699930, 2023). "OPN in the tumor microenvironment binds to CD44 expressed on PCSC properties, which subsequently promotes clonal growth, invasion, and metastasis." (PMID 37173787, 2023). "These mice also had more TRP2-specific CD62L+CD44+CD8+ T cells in the primary tumor-draining lymph node compared to the CBD–IL-12 monotherapy." (PMID 38019919, 2023).
tumor (continued). "Like SDC4, the CD44 cytoplasmic domain is reported to mediate cell migration through Rac1 and RhoA in human tumor cell lines." (PMID 36735684, 2023). "The results obtained in this study showed a co-eradication of CD44+ BCSCs as well as bulk tumor cells." (PMID 36899854, 2023). "It is proposed that ENO1's anti-tumor action is in part mediated by CD44 which is known to promote cell proliferation in breast cancer cell lines." (PMID 37056934, 2023). "ALDH1 staining was focal and restricted to the cytoplasm, while CD44 staining was widely expressed in the membrane of normal, dysplastic and tumor epithelial cells." (PMID 38126564, 2023). "CD44 is involved in the process of heterogeneous adhesion of tumor cells and plays a role in promoting the invasion and metastasis of tumor cells." (PMID 36980687, 2023). "Enrichment for the progenitor-like marker CD44 was observed mostly at the periphery of several tumoroids, as in the parental tumor tissue." (PMID 37736770, 2023). "We found that the control tumors were heterogenous, with many areas showing clusters of human tumor cells with CD44 immunopositivity." (PMID 37244935, 2023). "The hyaluronan/CD44 axis can modulate the tumor microenvironment, and this influences cancer progression and chemoresistance." (PMID 37958796, 2023). "PCSCs can be identified with cell surface markers expressed, and studies suggest that CD44 harbors them to exhibit tumor invasive properties." (PMID 36969009, 2023). "The levels of CD44+/CD24-cell enrichment on rough surfaces were equivalent to those in tumor spheroids, supporting relevant enrichment levels of the CSC phenotype." (PMID 36968199, 2023). "In BC, NK cells have been shown to reduce tumor growth in vivo and specifically kill CD44+CD24low/- BCSC from an HR+ cell line when activated with IL2 and IL15." (PMID 37445860, 2023). "P-selectin on the platelet membrane can specifically bind to CD44 on the surface of cancer stem cells (CSCs) to precisely target cancer cells and achieve tumor-targeting." (PMID 38140108, 2023). "Unexpectedly, we observed increased proportions of monocytes and IFNγ+CD44+ CD4+ T cells in anti–PD-1-treated KB1P tumor-bearing mice." (PMID 36480166, 2023). "Another meta‐analysis showed that the expression of stem cell marker CD44, a principal cell surface receptor for hyaluronic acid, was correlated with stage, tumour size, and metastasis of GC." (PMID 37118990, 2023). "An interesting study highlighted the strict correlation between HAS2 expression, HA/CD44 signaling, and ER-dependent tumor aggressiveness." (PMID 37568628, 2023). "In many cases, the intensity of the CD44 staining was significantly stronger at the periphery of tumorous infiltrates, i.e., the invasive tumor fronts." (PMID 38003753, 2023). "In HI-type GBM, CD44 expression tended to be much lower in the tumor core than in the tumor periphery." (PMID 37760811, 2023). "Colorectal sections of the mice (a tumor-prone site) were examined by immunohistochemistry (IHC) staining and iron-specific staining (Prussian blue) for the key proteins CD44 and SLC7A11." (PMID 36672372, 2023). "Cancer vaccine targeting CD44 biomarkers by using HA shows a therapeutic window for life-threatening cancer, where it serves as a critical player in self-restoration, tumor induction, metastasis, and chemoradioresistance." (PMID 36975676, 2023). "miR-3174 downregulated the expression of multiple tumor-promoting genes including CD44, MDM2, RHOA, PLAU and CDK6." (PMID 37298284, 2023). "CD44 expression suggests that the tumor is in a well-differentiated and gland-forming state as compared to Gleason's grade." (PMID 37461792, 2023). "Interactions of tumor cells with the BM microenvironment involve preferred communication with myeloid cells through the MIF/CD44/CD74/CXCR4 and MK/LRP1/NCL axes." (PMID 37365178, 2023). "Several studies indicate that Merlin exerts its tumor suppressor activity in part by negatively regulating CD44 function." (PMID 37174657, 2023).
tumor (continued). "CD44 is a multifunctional molecule that promotes the invasion and proliferation of tumor cells via various signaling pathways." (PMID 37835592, 2023). "Interaction between MCF7 cells and CD8+ T cells that have been treated with Concanamycin A, so they are unable to lysate tumor cells, has been shown to increase the population of CD44+/CD24− cells with stem properties." (PMID 37445860, 2023). "Another paper noted that S102 phosphorylation of YB-1 increased CD44 expression growth and enhanced tumor growth by mammosphere formation." (PMID 38037159, 2023). "The anti-CD44 antibody, as a tumor-target ligand, has been used to improve liposome accumulation in tumors by specifically interacting with CD44 receptors." (PMID 37513375, 2023). "CD44 is a membrane receptor for HA, and is an essential signaling molecule involved in tumor progression and metastasis, and the overexpressed CD44 is an unfavorable prognostic factor for CRC patients." (PMID 37161591, 2023). "Lastly, the loss of Arid2 promoted the expression of KLRD1 and inhibited TCF1 and TOX expression in the CXCR6+CD44+ cluster, further indicating an increased effector profile of tumor-specific CD8+ T cells following PBAF deletion." (PMID 37330910, 2023). "Using the MVN-on-a-chip model, it was revealed that tumor cells shed hyaluronic acid, which accumulates on ECs, thus priming their adhesion with tumor cell CD44 and promoting extravasation." (PMID 37064144, 2023). "In the CD24pos/CD49fpos sorted cell population, 40 out of 48 patients’ tumor cells had more than 80% of the cells positive for CD44." (PMID 37894373, 2023). "BCSC populations were more prevalent in TNBC, while differentiated tumor cells (ALDH-non-CD44+CD24-/low) were primarily found in Luminal A and HER2amp cells." (PMID 37771376, 2023). "P245, an anti-CD44 antibody, has been shown in murine models to decrease tumor progression and eradicate CSCs." (PMID 36675306, 2023). "As a result, the amount of soluble CD44 proteins in cancer patients' serum correlates with tumor growth and metastasis in various carcinomas." (PMID 36289579, 2023). "The CS part of SRGN promotes binding to CD44 on the surface of tumor cells, which then supports cell migration." (PMID 37108213, 2023). "CD44 marks an aggressive tumor-promoting CRC cell population and lumican (LUM) is a mesenchymal marker that is upregulated in CRC cells in collagen cultures during EMT." (PMID 37511344, 2023). "Currently, CD44 is an established cancer stem cell marker in several tumors, implying a central functional role in tumor biology." (PMID 37894408, 2023). "CD44 is a cell surface glycoprotein that has been extensively researched as a cancer-promoting molecule due to its crucial involvement in tumor development and progression." (PMID 37509716, 2023). "Their result established the possibility of conjugating an aptamer to siRNA-containing liposomes for efficacious gene silencing in CD44-expressing tumor cells in vivo." (PMID 37149607, 2023). "Aptamers are synthetic oligonucleotides capable of binding to specific targets; they have been used to target molecules overexpressed on the tumor cell surface, such as nucleolins and CD44, or in the tumor microenvironment, such as IL-4Rα." (PMID 36986798, 2023). "The adhesion molecule CD44 is a cell surface type 1 hyaluronan transmembrane glycoprotein receptor, and the inhibition of CD44 signaling has been found to be beneficial for the treatment of tumor patients." (PMID 37446885, 2023). "The TIMER database was used to explore the relationship between CD44 and PD-L1; CD44 and tumor-infiltrating immune cells." (PMID 37316699, 2023). "Together with E-cadherin, CD44 has been extensively studied in tumor cell differentiation, invasion, and metastasis, and is thought to be involved in the EMT process in HBC." (PMID 36899736, 2023).
tumor (continued). "We found that administration to mice of a blocking anti-CD44 mAb, significantly reduced tumor proliferation of AB22 naïve cells as well as that of shOPN AB1 cells." (PMID 37398648, 2023). "In a healthy brain, CD44 is involved in neuronal plasticity or development; however, in the context of cancer, it is related to tumor spread." (PMID 37174724, 2023). "Accordingly, it has been proposed that only cells expressing CD44 on the surface persist after chemotherapy treatment and are able to rebuild the tumor afterwards." (PMID 37958796, 2023). "The expression pattern of CD166 probably depends on the original tissue of the tumor, in the same way as for CD44." (PMID 36864434, 2023). "Further, we also demonstrated that miR-3174 downregulates multiple tumor-promoting genes (CD44, MDM2, CDK6, RHOA and PLAU) and all of these have been reported to have an important role in the development of various malignancies, including GBM." (PMID 37298284, 2023). "The tools predicted several tumor-promoting genes as a potential target of miR-3174 including CD44, CDK6, MDM2, RHOA and PLAU." (PMID 37298284, 2023). "In contrast, significant correlations were found for FAP, vimentin, CAIX, CD68 and CD44, thus indicating that tumoroids are able to retain the inter-tumor heterogeneity present in the tumor tissues." (PMID 37736770, 2023). "HA is an important component of the extracellular matrix (ECM), that along with its major cell surface receptor, CD44, promotes tumor progression in a variety of malignant neoplasms." (PMID 36766747, 2023). "The main ligand of CD44 is hyaluronan (HA), located in the tumor extracellular matrix, which activates signaling pathways associated with increased cell metastasis." (PMID 37759771, 2023). "HA accumulation in the tumor stroma, mediated by CD44, creates a supportive niche for cancer progression." (PMID 37958796, 2023). "Tumor cells overexpressing CD44 demonstrate numerous characteristics of cancer stem cells (CSCs), including the ability to self-renew, high potential for tumor initiation, capacity for epithelial–mesenchymal transition (EMT), and resistance to chemotherapy." (PMID 37509716, 2023). "CD44 is a multi-functional transmembrane glycoprotein, and the binding of CD44 to HA can promote various tumor cell activities." (PMID 37835592, 2023). "CD44 plays important roles in tumor progression and has various isoforms, which are generated by the alternative splicing of CD44 mRNA." (PMID 37489367, 2023). "Within this CD8+ T-cell numbers, it was observed that, there was 2–3-fold increase in activated and proliferating (Ki67+CD44+ in CD8+) T cells in the tumour in Vacc DC group as compared to the control groups." (PMID 37660049, 2023). "CD44 is the major HA receptor, and CD44 bound to HA participates in tumor biological activities including tumor progression, metastasis, and proliferation." (PMID 37593530, 2023). "The HI-type tumors with tumor invasiveness determined by 5-ALA intensity showed significantly greater P/C ratios of CD44 expression than LI-type tumors." (PMID 37760811, 2023). "We also observed that SPP1 gene mainly expressed in immune cells, whereas the CD44 mainly expressed in tumor cells." (PMID 37441593, 2023). "We then assessed by flow cytometry activation markers associated with effector function (CD69, CD44 and 2-NDGB) expressed on tumor infiltrating CD4+ and CD8+ T cells from anti-PD-1 and anti-PD-L1 refractory mice." (PMID 35355980, 2022). "Recently, CD44 was also identified as a typical surface marker for cancer stem cells, being a critical regulator of cancer stemness, self-renewal, tumor initiation, and metastases." (PMID 35456670, 2022). "A study by Zheng and colleagues explored the impact of linker rigidity in the context of a bsApt with affinity for two different tumor cell antigens (EpCAM and CD44)." (PMID 35141049, 2022). "CD44 has implications in tumor-progressing function, leading to tumor metastasis with poor prognosis." (PMID 36291969, 2022).